SDC1 (syndecan 1)
Diseases named in the same sentence as SDC1 in open-access papers (continued):
Sharing a sentence is not in itself a finding about the gene and the disease.
infection (88 papers, 2006 to 2026). The state of being infected such as from the introduction of a foreign agent such as serum, vaccine, antigenic substance or organism. "Lactoferrin, a potent iron-chelating glycoprotein, limits bacterial growth by depriving pathogens of essential nutrients, while syndecan-1 contributes to the stabilization of the urothelial glycocalyx, reducing bacterial penetration and subsequent infection risk." (PMID 39997066, 2025). "Activation of Sdc1 shedding is an innate host response to tissue injury that protects against inflammatory tissue damage but can also be a pathogenic response that promotes infection by dampening inflammatory host defense when stimulated in an untimely manner." (PMID 33293379, 2020). "Other studies also found protective effects of syndecan-1 deficiency during infections." (PMID 26832929, 2016). "Disease severity explained most syndecan-1 variance (19.2%), whereas pathogen category (6.7%) and infection site (2.2%) contributed little." (PMID 42312022, 2026). "Syndecan-1, which is bound to the endothelial cell surface, has been reported to be targeted by microbial pathogens, particularly in the early stages of infection, and to be involved in the initiation of acute inflammatory responses." (PMID 38839816, 2024). "Previous studies have shown that syndecan-1, is shed and released into the bloodstream during severe infection, reflecting glycocalyx damage and hence a superficial endothelial disruption." (PMID 36536028, 2022). "This review outlines the role of HPSE and SDC-1 as newly assigned host factors that facilitate HSV-1 release during a lytic infection cycle." (PMID 36298711, 2022). "Sdc1−/− corneas were also significantly protected from infection by S. pneumoniae strains M11 and D39, indicating that the ability of Sdc1−/− corneas to resist S. pneumoniae infection is not restricted to the TIGR4 strain." (PMID 33293379, 2020). "Immunostaining of eye sections showed a markedly reduced expression of Sdc1, most prominently at the site of infection, whereas the signal for Sdc4 was unaffected, confirming the biochemical shedding data." (PMID 33293379, 2020). "N2a cells were transfected with 50 nM of SDC1 siRNA-1, followed by infection of PHEV at 37°C for indicated times." (PMID 32153518, 2020). "We therefore tested the idea that S. pneumoniae co-opts Sdc1 as a cell surface attachment site to promote its infection." (PMID 33293379, 2020). "HCV also interacts with heparan sulfates on Syndecan 1 and Syndecan 4 which can facilitate attachment and infection in cell lines." (PMID 32292405, 2020). "Interactions of bacterial pathogens with heparan sulfate proteoglycans such as SDC-1 have been described as important steps in the pathogenesis of different infections." (PMID 30373658, 2018). "Some microbial pathogens subvert syndecan-1 to increase dissemination and host defense evasion during infection." (PMID 26832929, 2016). "Cells with silenced SDC1 expression were equally capable of HCVpp infection as cells that were either mock transfected or transfected with a nonspecific sequence as a control for silencing." (PMID 24751902, 2014). "As we found that CM contains considerable amounts of syndecan-1, likely in complex with GF, we predicted depletion of syndecan-1 from the CM would remove a substantial level of components needed for infection." (PMID 22346752, 2012). "HPV particles associate with GFRs at the keratinocyte plasma membrane and the removal of syndecan-1 HSPG or EGF inhibits infection." (PMID 22346752, 2012). "Depletion of syndecan-1 or epidermal growth factor and removal of serum factors reduce infection, while replenishment of growth factors restores infection." (PMID 22346752, 2012). "As expected, when the CM was stripped of syndecan-1 by IP, infection levels were reduced to levels close to those in SFM." (PMID 22346752, 2012).
infection (continued). "We further analyzed the effect of syndecan-1 knockdown on infectious virus titers after HSV-1 (KOS) infection utilizing HSV-1 growth curve assay." (PMID 21957484, 2011). "Syndecan-1 is a receptor for human immunodeficiency virus in cell culture and contributes to the pathology of infection by Pseudomonas aeruginosa and Staphylococcus aureus." (PMID 16620374, 2006). "One key area of investigation is whether urinary syndecan-1 levels correlate inversely with symptomatic UTI risk, which could establish its potential role as a biomarker for predicting susceptibility to infection." (PMID 39997066, 2025). "SDC1 promotes Streptococcus pneumoniae epithelial cells’ extracellular matrix attachment through its PavA protein, establishing a niche for cell growth and infection." (PMID 41440381, 2025). "SDC-1 ectodomains have been shown to inactivate cathelicidins and reduce neutrophil-mediated killing, significantly increasing staphylococcal survival during infection." (PMID 37486132, 2023). "Expression of syndecan-1 increased slightly after infection." (PMID 37939119, 2023). "In our model, the serum levels of syndecan-1 increased after infection (1.4-fold), and this may be the result of glycocalyx degradation." (PMID 37939119, 2023). "Serum syndecan-1 (102.84 ± 16.53 vs. 55.38 ± 12.34 ng/ml), and sTM(6.60 ± 1.44 ng/ml vs. 5.23 ± 1.23 ng/ml, P < 0.01) levels were increased in the septic group compared with those in the infection group." (PMID 36536028, 2022). "Taking these findings into account, we examined if Sdc1 deletion reduces or dysregulates the expression of E-cadherin, β1 integrins, or FN in corneas, which in principle should decrease S. pneumoniae adhesion and infection in Sdc1−/− corneas." (PMID 33293379, 2020). "Changes in SDC1 expression levels could be observed during infection with Pneumocystis and Neisseria gonorrhoeae." (PMID 32575635, 2020). "Sdc1-/- mice were reported to have abnormal phenotypes in injury and infection models." (PMID 26832929, 2016). "Thus, it should be emphasized that our conclusions regarding the effects of syndecan-1 on infection and inflammation are only relevant to the early acute inflammatory responses after 4 h of infection." (PMID 26832929, 2016). "Evidence has shown that syndecan-1 exhibits very strong localization within the corneal epithelium that represents one of the major infection sites for HSV-1 that may precede infection of other sites within the eye." (PMID 21957484, 2011). "The combined knockdown of SDC1 and the post-attachment receptor CD81 significantly reduced infection compared to either single knockdown, suggesting cooperative activity." (PMID 34205894, 2021). "Inhibition of syndecan-1 shedding by MMPs, ADAMs, and/or heparanase greatly reduces cellular uptake of HPV serotype 16 and subsequent infection." (PMID 34207476, 2021). "Especially, Syndecan 1 and Syndecan 4 have shown to be important attachment receptors for HCV on the surface of hepatocytes thereby facilitating infection." (PMID 32292405, 2020). "Syndecan-1 and sTM levels were significantly higher in patients with septic shock than in patients with infection and septic nonshock." (PMID 36536028, 2022). "First, both syndecan-1 and sTM levels were significantly increased in the septic shock group compared with those of the septic nonshock and the infection groups." (PMID 36536028, 2022). "During infection, HPV-16 mainly attaches to ECM components of keratinocytes through HS chains of syndecan-1, and the action of HSPG processing enzymes is relevant to the release of infectious viral particles from the ECM and to an efficient infection of keratinocytes." (PMID 34207476, 2021). "Neither focus of infection nor presence of shock or emergency surgery before admission influenced syndecan-1, thrombomodulin or protein C quartiles (data not shown)." (PMID 25907781, 2015).
infection (continued). "Silencing of either SDC1 or SDC4 prior to HCV challenge showed that while knockdown of SDC1 modestly but significantly diminished infection, SDC4 knockdown markedly inhibited infection." (PMID 24751902, 2014). "The emerging role of syndecan-1 during HSV-1 infection opens new doors that might add clarity to the picture of virus entry and infection." (PMID 21957484, 2011). "Delineating the role of syndecan-1 during the various HSV-1 infection events, especially those at the early stages of the infection is of significance as that might help the development of new antiviral agents or an effective HSV-1 vaccine." (PMID 21957484, 2011). "HCE cells were chosen to examine the contribution of syndecan-1 during HSV-1 plaque formation because corneal epithelium represents one of the major infection sites for HSV-1 and may precede infection of other parts within the eye." (PMID 21957484, 2011). "Furthermore, silencing Syndecan-1 reduces the adsorption of PCV2 and inhibits its infection." (PMID 39745447, 2025). "SDC1 and SDC4 receptors that were expressed by AECII cells in our tissue specimens likely recognized fibroblast collagens but also may have facilitated pneumocyte infection by M. tb." (PMID 40772762, 2025). "Moreover, PCV2 infection reinforced the interaction between CD81 and Syndecan-1, suggesting that PCV2 may utilize this interaction to promote its own infection." (PMID 39745447, 2025). "Syndecan-1 levels were significantly increased in the septic shock group (102.84 ± 16.53 ng/ml) compared with those of the septic nonshock (76.06 ± 10.51 ng/ml) and infection (55.38 ± 12.34 ng/ml) groups." (PMID 36536028, 2022). "They observed no substantial increase in SDC-1 transcripts or protein synthesis during infection." (PMID 36298711, 2022). "In order to test whether the high susceptibility of tonsil-derived plasma cells was due to increased attachment via CD138 (syndecan-1), we attempted to selectively neutralize KSHV entry by pre-treating cell-free virus particles with soluble recombinant CD138 (srCD138) protein prior to infection." (PMID 33075105, 2020). "Serum syndecan-1 concentrations on ICU admission were significantly increased in the septic shock group and septic nonshock groups compared with those of the infection group." (PMID 36536028, 2022). "These RNAi-based studies were later supported by CRIPSR knockouts of SDC1-4, where only the absence of SDC1 and SDC2 significantly reduced HCVcc attachment and infection." (PMID 34205894, 2021).
adenocarcinoma (16 papers, 2008 to 2025). A common cancer characterized by the presence of malignant glandular cells. "In more detail, during TGFβ-induced EMT in A549 adenocarcinoma cells, a loss of nuclear SDC1 is observed that is associated with EMT." (PMID 36358747, 2022). "A correlation between EMT and nuclear translocated SDC1 has been observed in epithelial origin A549 adenocarcinoma cells." (PMID 36358747, 2022). "Further studies revealed that SDC1 is expressed at the basolateral borders of normal colonic epithelial cells; however, in adenocarcinoma cells, SDC1 was found to be present around epithelial cell membranes and in the cytoplasm." (PMID 26293675, 2015). "A small fraction of adenocarcinomas have increased syndecan-1 staining in the local stroma." (PMID 18590537, 2008). "On adenocarcinoma cells, syndecan-1 was present around cell membranes and in cytoplasm." (PMID 18590537, 2008). "In a small fraction of adenocarcinomas, syndecan-1 was upregulated in the local stroma." (PMID 18590537, 2008). "In adenocarcinomas, SDC1 immunostaining was not present in some patient samples; however, it showed positive immunostaining in epithelial cells, in both Gleason 3 (low grade) and Gleason 4–5 adenocarcinomas (high grade)." (PMID 34445387, 2021). "We found that shed SDC-1 and MMP-7 levels were significantly lower, whereas Mesothelin and Galectin-1 levels were significantly higher in malignant mesothelioma effusions, compared to adenocarcinoma." (PMID 32731396, 2020). "In contrast, in the majority of the adenocarcinomas, syndecan-1 staining was decreased or absent." (PMID 18590537, 2008).
hematological malignancies (16 papers, 2012 to 2024). "In some instances, SDC1 overexpression is an adverse indicator for both solid and hematological malignancies." (PMID 23988031, 2013).
cardiovascular disease (15 papers, 2011 to 2025). "Increased shedding of the endothelial cell surface proteoglycans occurs during the cardiovascular disease process, and elevated levels of some of the components of the glycocalyx such as syndecan-1 have been observed." (PMID 37447199, 2023). "Among these genes, TYW1B, FCER2, SELE, and SDC-1 had some degree of connection with cardiovascular diseases including AF." (PMID 36078037, 2022). "This suggests that through syndecan-1, n-3 PUFA may have beneficial effects on lipoprotein homeostasis relative to cardiovascular disease." (PMID 21655218, 2011). "Interestingly, there was no strong relationship between the syndecan-1 levels and blood pressure, vascular access, cardiovascular disease, and primary disease before and after dialysis." (PMID 35004758, 2021).
kidney disease (13 papers, 2016 to 2025). "In epithelial cells, cell surface SDC1 is cleaved by inflammation-induced proteases (eg, ADAMTS, MMP), and loss of cell surface SDC1 is associated with higher susceptibility to cell damage, in gastroenterological, but also renal disorders." (PMID 30065042, 2018). "Of note, both hyaluronan and syndecan-1 are measurable in the urine in health and in disease, but the significance of urine concentrations of both molecules in the context of kidney disease is unclear." (PMID 33423673, 2021). "This study is the first to show on human kidney tissue that C5b-9 is deposited on the tubular brush border in various proteinuric human kidney diseases, with the activation mediated mainly via the alternative pathway, potentially initiated by properdin binding to syndecan-1." (PMID 41215783, 2025). "Syndecan-1 is a major membrane spanning HSPG in epithelial cells and has been shown to be upregulated on tubular epithelium in renal disease." (PMID 32849563, 2020). "Twenty-one kidney biopsies of different proteinuric kidney diseases were stained for complement components MASP-2 (lectin pathway), C1q (classical pathway), properdin (alternative pathway) and downstream complement activation (C3d and C5b-9), as well as syndecan-1." (PMID 41215783, 2025).
cerebral artery (7 papers, 2013 to 2025). "Batimastat (BB-94), a broad-spectrum MMP inhibitor that also inhibits SDC-1 shedding, reduces ascites and disrupts breast, ovarian and colorectal carcinogenesis." (PMID 35118073, 2021). "Under ischemic and hypoxic conditions (transient middle cerebral artery occlusion (t-MACO) model), the glycocalyx (GCX) undergoes enzymatic degradation, facilitating the interaction between syndecan-1 and Src by enhancing the binding of phosphorylated syndecan-1 to the Src SH2 domain." (PMID 40305173, 2025).
bacterial infection (5 papers, 2015 to 2022). "The loss of Sdc-1 as a result of genetic mutation reduces the susceptibility of mice to several bacterial infections." (PMID 36465208, 2022). "Previous studies have shown that Sdc1 can promote bacterial infection as a cell surface attachment receptor or as a soluble ectodomain inhibitor of innate host defense." (PMID 33293379, 2020). "Interestingly, the tissue bacterial load was similar in Wt and Sdc1-/- mice at 12 h pi, suggesting that Sdc1 ablation affects Lm pathogenesis after bacterial infection of intestinal tissues." (PMID 32453780, 2020). "It has also been reported that bacterial infection and propagation were not affected by Sdc-1, supporting our notion." (PMID 33930030, 2021). "Although the exact reason remains unknown, we speculate that differences in septic WT and Sdc-1 KO mice microvascular permeability are not mediated by the severity of bacterial infection." (PMID 33930030, 2021).
hematologic cancer (5 papers, 2015 to 2021). "Levels of SDC-1 expression have, however, been recognized as a prognostic marker in solid and hematologic cancers." (PMID 35118073, 2021).
inflammation (5 papers, 2016 to 2020). Aberrant reaction of the microcirculation characterized by movement of fluid and leukocytes from the blood into extravascular tissues. "Eotaxin is a chemokine that has been shown to increase osteoclast activity in bone inflammation, while syndecan-1 might be associated with attempted cartilage repair." (PMID 33396653, 2020). "Since the lung epithelium is damaged by high VT and syndecan-1 is expressed to regulate lung inflammation, we may postulate that syndecan-1 may also contribute to lung inflammation in VILI." (PMID 29670537, 2018).
benign neoplasm (3 papers, 2015 to 2021). A neoplasm which is characterized by the absence of morphologic features associated with malignancy (severe cytologic atypia, tumor cell necrosis, and high mitotic rate). "In conclusion, a high preoperative syndecan-1 concentration greater than 90 ng/mL was able to predict severe AKI after valvular heart surgery and was associated with prolonged hospitalization." (PMID 32531891, 2020). "In conclusion, a high preoperative syndecan-1 concentration greater than 90 ng/mL was an independent predictor of severe AKI after valvular heart surgery, and was associated with increased preoperative inflammatory tone and prolonged postoperative hospitalization." (PMID 32531891, 2020).
inflammatory myopathies (2 papers, 2023 to 2025). "Additionally, B-cell markers (MS4A1) and plasma cell markers (JCHAIN and SDC1) were significantly elevated compared to most other inflammatory myopathy groups, reaching levels akin to those seen in IBM muscle biopsies." (PMID 40568658, 2025).
metabolic disorders (2 papers, 2024 to 2025). "This suggests that syndecan-1 regulates the sensitive balance between osteoblast and adipocyte differentiation from MSCs, which is relevant in systemic metabolic disorders." (PMID 38912739, 2024).
infectious disease (1 paper, 2025). A disorder directly resulting from the presence and activity of a microbial, viral, or parasitic agent in humans. "Syndecan-1 is the dominant form of syndecans and is involved in the promotion of inflammation, infectious diseases, and tumors." (PMID 40564918, 2025).
SDC1 also shares sentences with these, for which no sentence is quoted: multiple myeloma (198 papers); monoclonal gammopathy of undetermined significance (15); endometritis (12); acute respiratory distress syndrome (9); non-Hodgkin lymphoma (6); lymphoplasmacytic lymphoma (5); plasma cell leukemia (5); Waldenström Macroglobulinemia (5); acute myeloid leukemia (4); anemia (4); endometrial polyp (4); head and neck carcinoma (4); multiple sclerosis (4); renal failure (4); ameloblastic carcinoma (3); amyloidosis (3); B-cell neoplasm (3); Burkitt lymphoma (3); cyst (3); Dyslipidemia (3); encephalitis (3); idiopathic pulmonary fibrosis (3); marginal zone lymphoma (3); medulloblastoma (3); Miscarriage (3); smoldering myeloma (3); thyroid cancer (3); acute appendicitis (2); acute lymphoblastic leukemia (2); acute myocardial infarction (2).
A further 173 diseases each share a sentence with SDC1 in 2 papers or fewer.